RELB (RELB proto-oncogene, NF-kB subunit)
Diseases named in the same sentence as RELB in open-access papers (continued):
Sharing a sentence is not in itself a finding about the gene and the disease.
squamous cell carcinoma (5 papers, 2015 to 2022). A carcinoma arising from squamous epithelial cells. "RelB cytoplasmic expression was higher in squamous-cell carcinomas compared to adenocarcinomas (P = 0.003)." (PMID 31586084, 2019). "As expected, PELI1 knockdown significantly promoted the accumulation of NIK proteins and thus enhanced the activation of the IR‐induced noncanonical NF‐κB signaling pathway in TE‐1, ECA‐109, SCC‐9 and SiHa squamous carcinoma cells, resulting in enhanced p52 and RelB entry into the nucleus." (PMID 34738714, 2022). "In addition, RelB nuclear expression was detected in higher levels in squamous carcinomas than adenocarcinomas (P = 0.039)." (PMID 31586084, 2019). "Similarly, RelB was present in both the nucleus and the cytoplasmic portions of the squamous cell carcinomas." (PMID 29983639, 2018). "High RelB expression was detected in 52.6% (20/38) the squamous cell carcinomas." (PMID 29983639, 2018). "The heterogeneity of RelB expression was observed in adenocarcinomas and squamous cell carcinomas." (PMID 29983639, 2018). "To comprehensively examine NF-κB expression in NSCLC, we analyzed serial sections of primary tumor samples from 77 well-documented patients (36 adenocarcinomas, 40 squamous cell carcinomas and 3 large cell carcinomas) for immunoreactivity of RelA, RelB, P50, and P52/P100." (PMID 26147201, 2015).
colon cancer (4 papers, 2017 to 2019). "Here, we systematically explored the functions of the alternative NF-κB subunit RelB in colon cancer cells and its underlying mechanism." (PMID 30473630, 2018). "Our results indicated that RelB affected many cellular behaviors of DLD-1 colon cancer cells including proliferation, migration, invasion, and chemo-sensitivity." (PMID 30473630, 2018). "The results suggested that of the RelB-silencing enhanced the sensitivity to 5-FU of the DLD-1 colon cancer cells." (PMID 30473630, 2018). "The study here was aiming to define the significance of RelB in colon cancer cells." (PMID 30473630, 2018). "The functions of RelB in DLD-1 colon cancer have not been addressed." (PMID 30473630, 2018). "However, different from previous reports, the RelB-silencing did not affect the survival of DLD-1 colon cancer cells." (PMID 30473630, 2018).
combined immunodeficiency (4 papers, 2021 to 2025). A broad classification of inherited disorders presenting at birth that affect both the cell-mediated and humoral aspects of the immune response. "RelB deficiency and c-Rel deficiency, reported for the first time in 2015 and 2019, respectively, are autosomal recessive forms of combined immunodeficiency (CID)." (PMID 40134438, 2025).
diffuse large B-cell lymphoma (4 papers, 2023 to 2025). "In Diffuse Large B-cell Lymphoma (DLBCL), elevated anti-apoptotic BCL2-family proteins (e.g., MCL1, BCL2, BCLXL) and NF-κB subunits (RelA, RelB, cRel) confer poor prognosis." (PMID 40819126, 2025). "Additionally, noncanonical NFKB signaling through RELB contributes to doxorubicin-induced glycolysis in doxorubicin-resistant diffuse large B-cell lymphoma cell lines." (PMID 38272231, 2024).
esophageal cancer (4 papers, 2014 to 2022). A primary or metastatic malignant neoplasm involving the esophagus. "The expression patterns of NF-κB subunit p65, c-Rel and RelB were similar in other three esophageal carcinoma cell lines." (PMID 24529193, 2014).
experimental autoimmune encephalomyelitis (4 papers, 2019 to 2024). An autoimmune demyelinating disease of the central nervous system that is produced experimentally in animals by the injection of homogenized brain or spinal cord in Freund's adjuvant. "Conversely, clinical severity of experimental autoimmune encephalomyelitis (EAE), a mouse model of multiple sclerosis (MS) was significantly reduced in mice with RelB-deficient T cells." (PMID 34608221, 2021). "Despite intensive research, the role of RelB in MS and its animal model, experimental autoimmune encephalomyelitis, is still unclear." (PMID 31881915, 2019). "We used experimental autoimmune encephalomyelitis (EAE), an accepted mouse model of MS, to assess the effect of RelB deletion on disease outcomes and performed analysis on the histological, cellular, and molecular level." (PMID 31362762, 2019).
melanoma (4 papers, 2018 to 2026). A malignant, usually aggressive tumor composed of atypical, neoplastic melanocytes. "The finding that the expression of RELB is upregulated in Atg5‐deficient TECs isolated from melanoma‐bearing mice, suggests a transcriptional mechanism." (PMID 38009521, 2023). "To exclude technical problems in our experiments, we also used a human melanoma cell line A375 as a control to determine the localization patterns of RelA, RelB, and CUL4B." (PMID 29377600, 2018). "Interestingly, levels of RelB and p52 were found to be elevated in melanoma cells cultured on fibroblast‐derived ECMs compared to plastic and collagen‐coated dishes." (PMID 34957688, 2022). "Indeed, targeting Polr1a decreased levels of RelB and p52 and suppressed non-canonical NF-κB transcriptional activity; this suppression was responsible for the effects of Polr1a on melanoma cell migration." (PMID 42310097, 2026). "Together, our findings suggest that melanoma cell adaptation to oncogenic MAPK pathway inhibition involves the interaction of tumor cells with the mesenchymal stroma enriched in fibrillar collagens, thereby promoting DDR‐dependent activation of the NF‐κB2/RelB pathway." (PMID 34957688, 2022).
B cell lymphomas (3 papers, 2016 to 2022). "Their downregulation after inactivation of RelB was of keen interest to us, as both genes are overexpressed in some B cell lymphomas." (PMID 36110848, 2022). "In sum, our data suggest that RelB accelerates the initiation and progression of B cell lymphomas by regulating genes involved in cell migration, proliferation and cytokine signaling." (PMID 36110848, 2022). "Since this mouse model substantially mimics the constitutive CD40-stimulation of B cells in a pathological situation in humans, we regarded it as a perfect tool to study the role of RelB and its regulated genes in the initiation and progression of B cell lymphomas." (PMID 36110848, 2022). "Assuming that in humans TRAF2 and TRAF3 mutations occur in premalignant cells, they may contribute to the initiation of B cell lymphomas through a similar RelB-dependent mechanism as we describe here for LMP1/CD40 mice." (PMID 36110848, 2022). "Although these findings hint at an important role of the non-canonical NF-ĸB signaling in the development of B cell lymphomas the contribution of RelB to lymphopathogenesis is still largely unknown." (PMID 36110848, 2022).
breast tumor (3 papers, 2007 to 2017). "Furthermore, it was also shown that MCPIP1 functions as a potent tumor suppressor and induces apoptosis of breast tumor cells by selectively enhancing mRNA decay of antiapoptotic gene transcripts, including Bcl2L1, Bcl2A1, RelB, Birc3, and Bcl3." (PMID 28197812, 2017).
hepatocellular carcinoma (3 papers, 2015 to 2026). A malignant tumor that arises from hepatocytes. "We further confirmed the change of RelB upon injury, and we treated hepatoma cells with CCl4 to induce injury in vitro." (PMID 32306539, 2020). "Knockdown the expression of RelB in hepatoma cells greatly reduced the expression of CCl4‐induced inflammatory cytokines." (PMID 32306539, 2020). "To determine the role of RelB in injury‐induced production of inflammatory cytokines, we knockdown the expression of RelB in hepatoma cells." (PMID 32306539, 2020). "Consistently, CCl4 treatment could up‐regulate the expression of RelB as well as inflammatory cytokines such as IL‐6 and TGF‐β1 in hepatoma cell as well as in WT mice." (PMID 32306539, 2020).
Hodgkins lymphoma (3 papers, 2013 to 2016). A heterogeneous group of malignant lymphoid neoplasms of B-cell origin characterized histologically by the presence of Hodgkin and Reed-Sternberg (HRS) cells in the vast majority of cases. "Inhibition of Notch-induced RelB/p52 activity in Hodgkin lymphoma cell lines is associated with apoptosis and decreased expression of cIAP2." (PMID 23555623, 2013).
liver fibrosis (3 papers, 2020 to 2022). "TNFSF14, which acts downstream of RelB, promotes hepatic stellate cell activation and exacerbates liver fibrosis." (PMID 36313114, 2022). "And found that RelB is essential for the release of inflammatory factors and fibrogenic factors in damaged hepatocyte, and the progression of hepatic fibrosis." (PMID 32306539, 2020). "In summary, we provide the genetic evidence to demonstrate the critical and hepatocellular role of RelB in liver fibrosis." (PMID 32306539, 2020). "Due to the critical role of RelB in mouse model, we examined the relevance of RelB in patients with liver fibrosis." (PMID 32306539, 2020). "Our results demonstrate a potential relevance of RelB in patients with liver fibrosis, and RelB is up‐regulated upon injury." (PMID 32306539, 2020). "In conclusion, we have analysed the role of non‐canonical NF‐κB signalling transcriptional regulator RelB for hepatocyte injury and liver fibrosis." (PMID 32306539, 2020). "We firstly analysed the expression of RelB in different fibrosis stages from patients with liver fibrosis." (PMID 32306539, 2020). "RelB expression is increased in chronic hepatitis C and promotes liver fibrosis." (PMID 33785040, 2021). "The Sirius red staining and Masson staining showed that knockout of RelB could significantly attenuate the degree of liver injury and inhibitor the development of hepatic fibrosis in Relb△hep livers compared with WT livers." (PMID 32306539, 2020). "Surprisingly, through constructing RelB hepatocyte‐specific knockout (Relb△hep) mouse model, we found that knockout of RelB could protect experimental hepatic fibrosis in mice." (PMID 32306539, 2020). "However, as a member of the NF‐κB family, the molecular mechanisms by which RelB promotes hepatocyte injury and hepatic fibrosis remain poorly understood." (PMID 32306539, 2020). "Furthermore, in patients with liver fibrosis, RelB is up‐regulated along with the stage of diseases." (PMID 32306539, 2020). "It suggests that RelB may play an important role in the progression of liver fibrosis in patients." (PMID 32306539, 2020). "Taken these results together, we found that knockout of RelB in hepatocyte could reduce the degree of liver injury, inhibit the activation of HSCs, reduce the deposition of ECM, thereby attenuate hepatic fibrosis." (PMID 32306539, 2020).
lupus (3 papers, 2021 to 2024). "Many genes contained in the Hallmark IFN-α response and Hallmark TNF-α signaling pathways, including IFI27, IFI44, RELB, KLF6, and CD83, had significantly higher expression in lupus: We verified transcriptional changes in the naive compartment by quantitative PCR (qPCR)." (PMID 39688922, 2024). "Increased expression of many TNF-α signaling genes, including RELB, accompanied the TNF-related enrichment in group 1 lupus participants." (PMID 39688922, 2024). "However, a much larger set of TFs contained in the TNF-α signaling gene set appeared among the active TFs in lupus cells; these include FOSL1, KLF6, RELB, BHLHE40, EGR3, and SMAD3." (PMID 39688922, 2024).
osteosarcoma (3 papers, 2012 to 2019). A usually aggressive malignant bone-forming mesenchymal neoplasm, predominantly affecting adolescents and young adults. "RelB has also been implicated in fostering the stemness of osteosarcoma cells through the paracrine action of cancer-associated mesenchymal stromal cells." (PMID 31586084, 2019). "We observed osteosarcoma cells had increased RelA, RelB, c‐Rel, and CUL4B levels in the cytoplasm and nucleus compared to hFOB1.19 cells, but not p50 and p52." (PMID 29377600, 2018). "RelA, RelB, and c‐Rel mRNA species were significantly up‐regulated in all four osteosarcoma cell lines compared to hFOB1.19 cells, with the highest expression being observed in c‐Rel (~eightfold), and similar effects were observed in RelA and RelB (~sixfold)." (PMID 29377600, 2018). "Consistent with the phenotypes of osteosarcoma cells, the up‐regulation of RelA, RelB, c‐Rel, and CUL4B in hFOB1.19 cells also led to increased colony formation and increased invasion." (PMID 29377600, 2018). "We found that in U2OS osteosarcoma cells, TNFα stimulates translocation of RELB and cREL between the nucleus and cytoplasm, with RELB being excluded from the nucleus and cREL accumulating in the nucleus." (PMID 22355351, 2012). "Given that RelA, RelB, and c‐Rel bind to the promoter region of CUL4B and regulate its expression, thereby causing CUL4B overexpression in osteosarcoma cells, we sought to determine whether the NF‐κB subunits were activated." (PMID 29377600, 2018). "As expected, osteosarcoma cells expressing lower levels of TNFR1, TNFR1 + RelA, TNFR1 + RelB, TNFR1 + c‐RelA, CUL4B, and CUL4B + RelA; SPD304‐treated cells; and p21‐overexpressing cells exhibited dramatically higher percentages of cells in the S phase." (PMID 29377600, 2018). "In addition, we also determined the localization patterns of RelA, RelB, p52, and CUL4B in clinical samples from patient 4, who was diagnosed with osteosarcoma at MSTS stage IV based on the histopathological features." (PMID 29377600, 2018).
schizophrenia (3 papers, 2020 to 2022). A major psychotic disorder characterized by abnormalities in the perception or expression of reality. "It is possible that this change in RelB mRNA in the blood of people with schizophrenia compared to controls reflects type 1 error." (PMID 35027554, 2022). "We found that elevations in TLR4 and RelB appear more related to inflammatory status than to a diagnosis of schizophrenia, but changes in TNFR2 occur in both the high and low inflammation patients (but were exaggerated in high inflammation patients)." (PMID 35027554, 2022). "Overall, leukocyte expression of the NF-κB-activating receptors, TLR4 and TNFR2, and the NF-κB subunit, RelB, was increased in people with schizophrenia compared to healthy control subjects (all p < 0.01), while NF-κB-inducing kinase mRNAs IKKβ and NIK were downregulated in patients (all p < 0.05)." (PMID 35027554, 2022). "This may also be the case in people with schizophrenia, where we also found that RelB is decreased in the dorsolateral prefrontal cortex." (PMID 32680547, 2020).
triple-negative breast carcinoma (3 papers, 2016 to 2020). An invasive breast carcinoma which is negative for expression of estrogen receptor (ER), progesterone receptor (PR), and human epidermal growth factor receptor 2 (HER2). "RelB uniquely expresses at a high level in aggressive BCa tissues, particularly in triple-negative breast cancer (TNBC)." (PMID 32807176, 2020). "This was further supported by a study from our group, which showed that EZH2 and RelA localized to the RelB promoter and supported transcription of RelB in triple-negative breast cancer cells." (PMID 29874793, 2018). "Our data identifies an HMT-independent role of EZH2 as a transcriptional activator of RelB in TNBC contributing to the maintenance of triple-negative breast cancer TICs." (PMID 27764181, 2016). "Since EZH2 promotes RelB production and tumor initiating cells in triple-negative breast cancer, it is interesting to consider what effects NIK stabilization may have on EZH2-RelB crossregulation." (PMID 29874793, 2018). "Interestingly, EZH2 was also found to support NF-κB target gene expression in triple-negative breast cancer cells by acting as a coactivator in a complex containing RelA and RelB." (PMID 29874793, 2018). "Here we show that EZH2, through a methyltransferase-independent mechanism, promotes the transcriptional activation of the non-canonical NF-κB subunit RelB to drive self-renewal and the TIC phenotype of triple-negative breast cancer cells." (PMID 27764181, 2016).
acute kidney injury (2 papers, 2010 to 2025). Sudden and sustained deterioration of the kidney function characterized by decreased glomerular filtration rate, increased serum creatinine or oliguria. "Increased tubular nuclear RelB and tubular CCL21 expression in acute kidney injury were decreased by neutralization (2±0.9 vs 1.3±0.6-fold over healthy control) or deficiency of TWEAK (2±0.9 vs 0.8±0.6-fold over healthy control)." (PMID 20126461, 2010). "Further significantly upregulated transcripts related to inflammatory processes included ADAM19, PD-L1 (CD274), non-canonical NF-kB genes NFKB2 and RELB, furthermore IFITM1, JAML -linked with acute kidney injury - IRX3-linked with metabolic inflammation - and PRDM1-observed in gouty arthritis." (PMID 40281125, 2025).
Arthritis (2 papers, 2017 to 2019). Inflammation of a joint. "In murine collagen-induced arthritis (CIA) model, we demonstrated that progression of arthritis was inhibited with administration of RelB gene-silenced Tol-DC or MSC." (PMID 28230210, 2017). "The RelB gene plays an important role in guiding the progression of arthritis." (PMID 30949517, 2019).
atopic dermatitis (2 papers, 2017 to 2024). "RelB-deficient mice develop skin lesions similar to atopic dermatitis, pointing to a tolerogenic role for RelB in the skin and may be LCs." (PMID 28690613, 2017).
Chronic Obstructive Lung Disease (2 papers, 2014 to 2015). "Utilizing blood samples from subjects participating in the Canadian Chronic Obstructive Lung Disease (CanCOLD) platform, we found that there was a significant positive correlation between systemic RelB and Cox-2 mRNA expression." (PMID 25943190, 2015).
cognitive disorder (2 papers, 2021 to 2023). A disease affects cognitive processes. "RELB, a TF for NF-kappaB, plays an important function in endothelial cells, which are vital components of the circulatory system and are partially involved in the development of HF and cognitive impairment." (PMID 34595235, 2021). "The results showed that the RELB high-expression group was enriched to KEGG_RETINOL_METABOLISM (P = 0.032) and KEGG_GAP_JUNCTION (P = 0.032), suggesting that the role of the regulatory axis may be similar in the development of HF and cognitive impairment." (PMID 34595235, 2021). "The hsa-miR-933/RELB/CCL21 regulatory axis was considered a potential culprit in the development of both HF and cognitive disorders." (PMID 37288268, 2023). "This work will generate fresh insight into the theoretical basis for clinical translation by demonstrating that the hsa-miR-933/RELB/CCL21 regulatory axis played an important role in HF and cognitive disorders." (PMID 34595235, 2021). "We will also explore the mechanisms of the hsa-miR-933/RELB/CCL21 regulatory axis in the development of HF and cognitive disorders by performing animal and cellular experiments." (PMID 34595235, 2021). "Based on PPI networks, the hsa-miR-933/RELB/CCL21 regulatory axis was considered a potential culprit in the development of both HF and cognitive disorders." (PMID 34595235, 2021). "The findings suggested a potential hsa-miR-933/RELB/CCL21 regulatory axis correlated with HF and neurological disorders (or cognitive impairment), according to PPI networks." (PMID 34595235, 2021). "The hsa-miR-933/RELB/CCL21 regulatory axis was speculated to function critically in HF and cognitive disorders." (PMID 34595235, 2021).